TLR4 (toll like receptor 4)
Diseases named in the same sentence as TLR4 in open-access papers (continued):
Sharing a sentence is not in itself a finding about the gene and the disease.
ocular hypertension (9 papers, 2019 to 2024). Abnormally high intraocular pressure. "We also demonstrated that mutation in Tlr4 blocked TGFβ2-induced ocular hypertension in mice." (PMID 32555351, 2020). "Mice harboring both the constitutively active EDA isoform and knock out alleles of TLR4 (B6.EDA+/+TLR4−/− mice) exhibited normal IOP and were resistant to TGFβ2-induced ocular hypertension." (PMID 35619185, 2022). "By utilizing our TGFβ2-induced ocular hypertension model, we have identified toll-like receptor 4 (TLR4) signaling as a novel molecular pathway involved in the development and progression of glaucomatous TM damage." (PMID 35216043, 2022). "Our group has shown that there is crosstalk between the TGFβ2 and TLR4 signaling pathways in the TM and that this crosstalk is contributing to glaucomatous ocular hypertension." (PMID 35912101, 2022). "It was recently reported that the extra domain A of fibronectin and the Toll-like receptor 4 (TLR4) contribute to transforming growth factor beta 2 induced ocular hypertension." (PMID 33668263, 2021). "These transgenic mice provide a means to study the function of the EDA isoform and its dependence on Tlr4 in a controlled strain specific manner using our inducible model of ocular hypertension." (PMID 32555351, 2020). "Here, e.g., the extra domain A of fibronectin was recently described to elevate IOP through TLR4 signaling in a TGFβ2-induced ocular hypertension mouse model." (PMID 33162981, 2020). "Previously, we identified that EDA-induced ocular hypertension was dependent on TLR4." (PMID 35619185, 2022). "Importantly, the effect of EDA+/+ on ocular hypertension was dependent on TLR4." (PMID 32555351, 2020). "We utilized transgenic mouse strains that either constitutively express only FN containing the EDA isoform or contain an EDA-null allele and express only FN lacking EDA, with or without a mutation in Tlr4, in our inducible mouse model of ocular hypertension by injection of Ad5.TGFβ2." (PMID 32555351, 2020). "We have previously identified that EDA-induced ocular hypertension and EDA-induced ECM production is dependent on TLR4." (PMID 35619185, 2022). "Previously, we utilized several transgenic mouse strains to determine that both TLR4 and the EDA isoform of FN are necessary for TGFβ2-induced ocular hypertension." (PMID 35619185, 2022). "We have previously shown that TGFβ2-induced ocular hypertension is dependent on both FN-EDA and its receptor toll-like receptor 4 (TLR4)." (PMID 35619185, 2022). "In conclusion, we have demonstrated that both Tlr4 and FN-EDA are necessary for TGFβ2-induced ocular hypertension." (PMID 32555351, 2020). "We investigated the role of an endogenous Toll-like receptor 4 (TLR4) ligand, fibronectin-EDA (FN-EDA), in TGFβ2-induced ocular hypertension in mice." (PMID 32555351, 2020). "We also identified that TGFβ2-induced ocular hypertension is dependent on both EDA and TLR4." (PMID 35619185, 2022). "TLR4 null and EDA null mice blocked Ad5.TGFβ-induced ocular hypertension." (PMID 32555351, 2020). "In order to determine whether FN-EDA and TLR4 are necessary for Ad5.TGFβ2-induced ocular hypertension phenotype, we tested wildtype C57BL/6J (n = 17), B6.TLR4−/− mice (n = 8), B6.EDA+/+ mice, B6.EDA−/− (n = 18), B6.EDA−/− /TLR4−/− (n = 23) and B6.EDA+/+/ TLR4−/− (n = 16) mice in our model system." (PMID 32555351, 2020). "Here, we identify the importance of FN-EDA in the development of ocular hypertension using transgenic mice that either constitutively express the EDA isoform or contain an EDA null copy, with or without knockdown of Tlr4." (PMID 32555351, 2020).
Opportunistic infection (9 papers, 2012 to 2026). An infection that is caused by a pathogen that would generally not be able to cause an infection in a host with a normal immune system. "This is an important distinction, since a fraction of humans has genetic deficiencies in the TLR4 pathway, which results in a plethora of opportunistic infections." (PMID 30726291, 2019). "Pseudomonas aeruginosa is known for opportunistic infections in burn patients through the use of a toll-like receptor-4 (TLR-4) associated lipopolysaccharide receptor complex to induce an inflammatory and adaptive immune response." (PMID 29734688, 2018). "TLR4 896 A > G and TLR4 1196 C > T SNPs were also determined to be significantly associated with more frequent opportunistic infections and cytomegaly, diagnosed among renal transplant recipients (RTRs)." (PMID 28340580, 2017). "Renal transplant recipients (RTRs), who carried TLR4 896 A>G and TLR4 1196 C>T SNPs, demonstrated more frequent opportunistic infections and cytomegaly." (PMID 25844529, 2015). "Increased expression of TLR2 and TLR4 has been reported in the myeloid dendritic cells of HIV-1 patients co-infected with opportunistic infections (without HAART)." (PMID 37298575, 2023). "Increased expression of TLR4 has been reported in plasmacytoid dendritic cells compared to both HIV-1 patients without opportunistic infections and healthy subjects." (PMID 37298575, 2023). "Dendritic cells obtained from HIV-infected individuals co-infected with M. tuberculosis have increased expression of TLR2 and TLR4, which may promote HIV replication and contribute to the faster disease progression observed in patients with opportunistic infections." (PMID 22844428, 2012).
osteonecrosis (9 papers, 2014 to 2025). A none disease characterized by death of bone tissue due to a lack of blood supply. "The DEGs in group G2 were primarily involved in proteolysis, TLR4 pathway, and negative regulation of the Wnt pathway, which are known to be involved in the osteonecrosis of the femoral head." (PMID 37303951, 2023). "Toll-like receptor 4 (TLR4) takes part in the anti-apoptotic role of miR-186 in podocytes and in the process of steroid-induced osteonecrosis." (PMID 33995003, 2021). "Possibly, steroid-induced osteonecrosis arises due to the activation of the TLR4 signaling pathway that sets the destructive mechanisms in train." (PMID 24428851, 2014). "In glucocorticoid-induced osteonecrosis of the femoral head in rats, calycosin, administered at a dosage of 10 mg/kg, promotes bone formation, inhibits the TLR4/NF-κB pathway, and significantly regulates inflammation, thus effectively alleviating osteonecrosis of the femoral head." (PMID 39210410, 2024). "The TLR4 pathway is pivotal in the progression of steroid-induced osteonecrosis." (PMID 33995003, 2021). "TLR4 stimulation and corticosteroid interactively induce osteonecrosis of the femoral head in rats." (PMID 33995003, 2021). "Accordingly, the objectives of this study were to clarify the pathogenesis of steroid-induced femoral head osteonecrosis and investigate the role of immune response disorder in osteonecrosis via TLR4 signaling pathway using a rat model of steroid-induced femoral head osteonecrosis." (PMID 24428851, 2014). "TLR4 signaling pathway could play an important role in the activation of osteoclast and the pathogenesis of osteonecrosis." (PMID 24428851, 2014). "TLR4 signaling pathway could play an important role in the pathogenesis of osteonecrosis." (PMID 24428851, 2014). "In the current study, the TLR4/NF-κB pathway and inflammation (IL-6, IL-10, and TNF-α) significantly increased after osteonecrosis induction by LPS with MPS." (PMID 28931847, 2017). "In osteonecrosis, elevated FSTL1 promotes NF-κB-dependent cytokine release and tissue degradation, while in infections and chondrocytes, it drives inflammation via TLR4/NF-κB and MMP induction." (PMID 40808692, 2025). "Inhibition of TLR4/MyD88/NF-κB signaling in vivo by calycosin or TLR-4 inhibitor TAK-242 reduced the expression of various pro-inflammatory factors and promoted bone formation, effectively alleviating osteonecrosis in animals with SONFH and in bisphosphonate-related osteonecrosis of the jaw." (PMID 36582244, 2022).
pancreatic ductal adenocarcinoma (9 papers, 2012 to 2024). An infiltrating adenocarcinoma that arises from the epithelial cells of the pancreas. "There was only one study evaluating the relationship between TLR4 and OS in pancreatic ductal adenocarcinoma (HR = 3.85, 95% CI (2.27, 6.53); P < 0.05)." (PMID 29560134, 2018). "In pancreatic ductal adenocarcinoma an increased expression of TLR4 has been detected compared to adjacent normal tissue." (PMID 28572836, 2017). "Previous studies demonstrated that, in pancreatic ductal adenocarcinoma, TLR2 and TLR4 serve as positive predictors of prognosis in stage I and II disease and in patients with small-size tumors." (PMID 32424768, 2020). "In pancreatic ductal adenocarcinoma (PDAC), TLR4 was expressed in the tumor cells and was related to the survival of patients with PDAC." (PMID 22985132, 2012).
Peri-Implantitis (9 papers, 2020 to 2025). An inflammatory process with loss of supporting bone in the tissues surrounding functioning DENTAL IMPLANTS. "Our previous studies showed that TLR2 are associated with implant bone loss in a mouse model of peri-implantitis and TLR4 is essential for periodontal bone loss." (PMID 32291538, 2020). "Taken together, miR-146a in addition to anti-RANKL antibody can further reduce bone loss in WT mice but is ineffective when TLR2 and TLR4 are deficient, suggesting miR-146a anti-bone loss effects in peri-implantitis are TLR2/4 dependent." (PMID 32291538, 2020). "Based on the findings, downregulating TLR2 and TLR4 in cells is the most direct and effective method for controlling peri-implantitis." (PMID 39555067, 2024). "Previous research has explored the therapeutic effect of anti-RANKL antibody (500 μg/mL) with or without microRNA 146a (miR-146a) (100 nM) towards C57/BL6 wild-type (WT) mice and TLR2-/-TLR4-/- (TLR2/4 KO) peri-implantitis mice models." (PMID 39555067, 2024). "Our data showed that the levels of TLR2, TLR4, IRAK1, and TRAF6 gene expression were in agreement with that in bone loss, suggesting peri-implantitis augmented by glycemic fluctuation were at least partly mediated through the activation of TLR2/4 signaling." (PMID 34401982, 2021). "Finally, the potential target genes, namely, IL-6, TLR4, FN1, IL-1β, CXCL8, MMP-9, and SPP1, were found to be associated with peri-implantitis, and our results were consistent with those of previous studies." (PMID 34931168, 2021). "Among these genes, IL-6 and TLR4 showed the highest node degrees, suggesting that they may play important roles in peri-implantitis." (PMID 34931168, 2021). "However, little is known about whether the TLR4 can regulate cytokines expression in the experimental animal model with peri-implantitis." (PMID 38359267, 2024). "However, little is known about the functions of TLR2 and TLR4 signaling in peri-implantitis." (PMID 32291538, 2020). "The intersecting genes, including IL6, TLR4, FN1, IL1β, CXCL8, MMP9, and SPP1, were revealed as potential genetic biomarkers and target genes of peri-implantitis." (PMID 34931168, 2021). "There is also a TLR4 signaling pathway that may influence B-cell infiltration and the RANKL/OPG ratio in peri-implantitis, thus modulating the inflammatory response." (PMID 37232785, 2023). "We found that IL-6, TLR4, FN1, IL-1β, CXCL8, MMP-9, and SPP1 might be used as potential biomarkers for the diagnosis of peri-implantitis." (PMID 34931168, 2021). "Studies have identified key differentially expressed genes (e.g., TLR4, CXCL8, FLT3, and IL1B), immune cell infiltration profiles (e.g., CD4+ T cells and macrophages), and microbiome signatures (e.g., distinct Fusobacterium nucleatum clades) in peri-implantitis." (PMID 40981185, 2025). "This study provides supportive evidence that IL6, TLR4, FN1, IL1β, CXCL8, MMP9, and SPP1 might be used as potential target biomarkers for peri-implantitis which may provide further therapeutic potentials for peri-implantitis." (PMID 34931168, 2021).
transient cerebral ischemia (9 papers, 2010 to 2025). "TM likely exerts the neuroprotective effects of promoting M1 to M2 microglial polarization by inhibiting JNK/TLR4/T3JAM/NF-κB-mediated signaling in the cortical ischemic rim 2 days after transient cerebral ischemia." (PMID 39391701, 2024). "However, 0.5 and 1 g/kg TM restored these levels of p-JNK and TLR4 in the cortical ischemic rim, reducing the interaction between JNK- and TLR4-mediated inflammatory cascades in microglia in the acute stage after transient cerebral ischemia." (PMID 39391701, 2024). "Furthermore, the expression of TLR4 was up-regulated in transient cerebral ischemia, and TLR4-defcient decreased infarct volumes, improved neurobehavioral function and suppressed inflammation after ischemic brain injury." (PMID 29922127, 2018). "Here, we determined whether the anti-inflammatory effects of sevoflurane postconditioning were mediated via inhibition of the toll-like receptor (TLR)-4/nuclear factor kappa B (NF-κB) pathway after global transient cerebral ischemia in rats." (PMID 29113143, 2017). "Among diverse TLRs, it has been reported that, after transient cerebral ischemia, induction of TLR2 predominates among TLRs, followed by TLR4 and TLR9." (PMID 22873409, 2012). "Astragaloside IV might exert anti-inflammatory effects by inhibiting toll-like receptor 4 (TLR4) signaling pathway and nucleotide binding oligomerization domain-like receptors P3 (NLRP3) inflammasome overactivation in order to prevent transient cerebral ischemia and reperfusion injury." (PMID 29358972, 2017).
AIDS (8 papers, 2009 to 2024). A syndrome resulting from the acquired deficiency of cellular immunity caused by the human immunodeficiency virus (HIV). "Moreover, the results of network pharmacology and experimental validation showed that DWYG could restore the immune function of acquired immune deficiency syndrome patients by inhibiting the expression of TLR4 and related signaling pathways and the overactivation of immune function." (PMID 39568580, 2024). "This indicates that DWYG can inhibit the overactivation of immune function and plays a significant role in the recovery or reconstruction of immune function in patients with AIDS by downregulating the expression of TLR4 in peripheral blood monocytes and related signaling pathways." (PMID 39568580, 2024). "In total, 23 SNPs in the TLR2, TLR4, and TLR9 genes, which may influence the susceptibility of AIDS patients to TM, were checked by the time of flight mass spectrometry (TOF/MS) method among these Han Chinese subjects." (PMID 33777838, 2021). "The SNPs within the TLR2, TLR4, and TLR9 genes that may contribute to an increased susceptibility of AIDS patients to TM were checked by the time of flight mass spectrometry (TOF/MS) method." (PMID 33777838, 2021). "Further study on the role of TLR4 and TLRs in restoring immune function in INRs can provide a new and important theoretical basis for the research and development of Chinese medicine immune regulation drugs, and provide new methods and approaches for the clinical treatment of AIDS." (PMID 39568580, 2024). "TLR4 encodes for a PRR mediating the inflammatory response to microbial translocation (e.g., bacterial endotoxin products such as lipopolysaccharide, which are significantly higher in people with HIV compared to uninfected individuals and are associated with AIDS progression)." (PMID 38019897, 2023). "And TAK-242 is also a TLR4 inhibitor that could reduce NET formation, suggesting that it may be helpful in treating AIDS." (PMID 36776836, 2023). "Among the study subjects, the susceptibility of AIDS patients to TM seems to be independent of the selected TLR2, TLR4, and TLR9 polymorphisms." (PMID 33777838, 2021). "Specifically, HIV RNA may influence the response to microbial translocation through TLR4 signaling, and promote or enable the cycle of immune activation and burn out that ultimately contributes to HIV immune dysfunction and AIDS." (PMID 19461969, 2009). "On the other hand, activation of PRR pathways such as TLR2 and TLR4 may lead to inflammation, promoting HIV replication and accelerating the progression of AIDS, while TLR7 and TLR8 may increase the expression of NF-κB, inhibiting HIV replication and delaying the progression of AIDS in ECs/LTNPs." (PMID 35211115, 2022).
alcoholic fatty liver disease (8 papers, 2015 to 2025). Lipid infiltration of the hepatic parenchymal cells that is due to alcohol abuse. "Interestingly, increased TLR4 signaling has also been associated with alcoholic steatohepatitis." (PMID 29342182, 2018). "Baicalin and chlorogenic acid suppress TLR4-mediated inflammatory signaling pathway by reducing hepatic level of TLR4 and MyD88 protein expression in I/R-treated animal model of alcoholic fatty liver disease and CCl4-fibrotic rats, respectively." (PMID 25954568, 2015). "Moreover, berberine diminished inflammation and lowered the levels of TNF-α, IL-6, and IL-1β in rats with non-alcoholic fatty liver disease by regulating the TLR4/MyD88/NF-κB signaling pathway." (PMID 38790653, 2024). "Further studies have shown ROF’s ability to suppress alcoholic fatty liver disease by maintaining the antioxidant balance in hepatocytes, upregulating GSH and SOD, downregulating CYP2E1 and TLR4, and decreasing the phosphorylation of NF-κB." (PMID 40689212, 2025). "This macrophage activation, via TLR4 signaling, and subsequent increase of inflammatory cytokines is a common mechanism of NASH and alcoholic steatohepatitis." (PMID 29342182, 2018). "Alpha ketoglutarate did not modulate cytokines’ level and toll-like receptor 4 expression in non-alcoholic fatty liver disease patients." (PMID 26629827, 2015).
ankylosing spondylitis (8 papers, 2005 to 2025). An autoimmune chronic inflammatory disorder characterized by inflammation in the vertebral joints of the spine and sacroiliac joints. "In ankylosing spondylitis, TLR4 (23.1 ± 21.9%) and, to a smaller extent, TLR2 (4.1 ± 5.8%) were expressed on CD4+CD28null T cells, whereas expression was negligible on CD4+CD28+ and CD8+ T cells." (PMID 16277694, 2005). "Another study reported that anti-TNF treatment decreases TLR5 (and TLR4) expression among ankylosing spondylitis patients, which supports the hypothesis of TLR5 having a role in the differential anti-TNF response." (PMID 26440629, 2015). "In another study, it was reported that infliximab decreased the expression of TLR-4 and TLR-5, the study indicated that higher TLR-4 and TLR-5 expression exacerbated inflammatory conditions in ankylosing spondylitis." (PMID 38521924, 2024).